NF1 (neurofibromin 1)
Diseases named in the same sentence as NF1 in open-access papers (continued):
Sharing a sentence is not in itself a finding about the gene and the disease.
neurofibroma (continued). "Peripheral nerve glial cells, Schwann cells (SCs), are the only cell type in neurofibromas that shows bi-allelic loss-of-function mutations in the NF1 tumor suppressor gene." (PMID 35311647, 2022). "It was interesting that this mutation was described in nine NF1 patients with a very high number of neurofibromas, including two individuals with metastasized MPNSTs." (PMID 35885913, 2022). "Individuals with p.Met992del appear to be at a significantly reduced risk of developing visible neurofibromas, malignant sequelae and other significant NF1-related health complications compared to classical, unsegregated NF1 cohorts." (PMID 34897289, 2022). "Low-grade MPNSTs are uncommon (10% of all MPNSTs) and usually arise from a pre-existing NF1-associated neurofibroma." (PMID 35741273, 2022). "Most likely, CALM (and other NF1-associated symptoms such as neurofibromas or freckling) in patients with CMMRD are caused by postzygotic NF1 mutations." (PMID 34928431, 2022). "In NF1, malignant peripheral nerve sheath tumours and benign neurofibromas differ in their mutational spectrum of the second hit." (PMID 34997843, 2022). "The influence of systemic metabolic alterations on timing and development of neurofibromas and other NF1-associated neoplasms need to be more explored in future studies." (PMID 36064430, 2022). "Other NF1-associated features such as Lisch nodules, neurofibromas, NF1-specific bone lesions, optic pathway gliomas, and malignant peripheral nerve sheath tumours are however absent in patients with Legius syndrome." (PMID 34928431, 2022). "Up to half of patients with NF1 develop benign nerve sheath tumors called plexiform neurofibromas (PNs), characterized by biallelic NF1 loss." (PMID 35741605, 2022). "Plexiform neurofibroma (PN), a significant cause of clinical complications in NF‐1, is a benign tumor of the peripheral nerve sheath that involves multiple nerve fascicles." (PMID 35506373, 2022). "Comprised of neoplastic Schwann cells, primary risk factors for developing MPNST include existing plexiform neurofibromas (PN), prior radiotherapy treatment, and expansive germline mutations involving the entire NF1 gene and surrounding genes." (PMID 35244537, 2022). "Neurofibromas are a hallmark feature of NF1 and are divided into subtypes, including cutaneous, subcutaneous, and plexiform neurofibromas." (PMID 36233563, 2022). "Currently, a phase II trial with a different MEK inhibitor is ongoing for adolescents and young adults with NF1-associated plexiform neurofibromas (NCT02096471)." (PMID 36358751, 2022). "NF1 is an autosomal dominant genetic syndrome due to mutations in the NF1 tumor suppressor gene and is characterized by café au lait spots, dermal and plexiform neurofibromas, pheochromocytomas, optic gliomas, and malignant peripheral nerve sheath tumors." (PMID 36387865, 2022). "Patients with whole-gene deletions of NF1, subcutaneous neurofibromas, or a larger number of plexiform neurofibromas are at particular risk of developing MPNST." (PMID 35053663, 2022). "This approach has also seen relatively well-documented success in other NF1-associated tumors, including low-grade gliomas (LGGs) and plexiform neurofibromas, with formal clinical trial assessment underway." (PMID 35053663, 2022). "The majority of NF1-associated symptoms (including pigmentary lesions, pseudarthrosis, neurofibromas, and other tumors) are due to the complete loss-of-function of the NF1 gene (resulting from the somatic inactivation of the NF1 wild-type allele)." (PMID 34199217, 2021). "It is caused by mutations in the NF1 gene, leading to neurofibromas, which are peripheral nerve sheath tumors derived from Schwann cells." (PMID 34070895, 2021). "Of interest, studies showed that neurofibromas caused by NF1 mutation most often transition to malignant peripheral nerve sheath tumor through the co-mutation of PRC2 subunit genes and CDKN2A." (PMID 34090875, 2021).
neurofibroma (continued). "It is now conceivable that NF1-deficient neurofibromas can be treated by targeting epigenetic mechanisms that reinforce RAS signaling and its association with inflammation." (PMID 33436083, 2021). "Patients with autosomal dominantly inherited NF1 are prone to develop benign peripheral nerve tumours known as neurofibromas, which is the hallmark of the disease." (PMID 35008787, 2021). "Eventually, NF1 variants were found to correlate with volumetric imaging features of neurofibromas depending on their type and localization." (PMID 33919865, 2021). "As discussed by Brosseau and collaborators, it is known that the Nf1+/− microenvironment contributes to neurofibroma development, but the underlying molecular and cellular mechanisms are elusive." (PMID 34445326, 2021). "Within neurofibromas, different cell types including NF1-deficient Schwann cell-like cells, fibroblasts, perineurial-like cells, neural cell elements (mainly processes) and recruited mast cells co-exist and grow." (PMID 32748156, 2021). "NF1 is caused by mutations in the Neurofibromin gene, and is characterized by pigmentary lesions, peripheral nerve tumors (neurofibromas and malignant peripheral nerve sheath tumors), skeletal abnormalities and brain tumors." (PMID 34179044, 2021). "Identified risk factors for malignant transformation are NF1 whole gene deletions, large whole-body tumor burden and a high number of subcutaneous neurofibromas." (PMID 33951044, 2021). "A systematic review of 157 cases of MNF1 published between 1977 and 2012 found that 11.5% had plexiform neurofibromas, 29% had NF1-associated complications and 13% had a risk of malignancy, especially if they had neurofibromas." (PMID 33853649, 2021). "Other risk factors for growth of NF1-associated tumors are young age, large whole-body tumor burden, female sex and a high number of subcutaneous neurofibromas." (PMID 33951044, 2021). "While loss of the neurofibromin allele in Schwann cells is known to be the initial trigger, their stem cell factor secretion drive NF1-gene-deficient mast cells into the neurofibroma lesion." (PMID 33530415, 2021). "Chimeric Nf1−/− mice harbor many of the hallmark features of NF1 disease including neurofibroma, asserting the need for biallelic inactivation in neurofibroma development." (PMID 34359780, 2021). "Further, patients with type-1 NF1 deletions frequently exhibit high numbers of neurofibromas and have an increased risk of malignant peripheral nerve sheath tumours." (PMID 34535841, 2021). "The age of the patient, tumor location, and evidence of progression from benign neurofibroma to MPNST are analogous to NF1-associated MPNST, which most commonly arise from benign congenital plexiform neurofibromas associated with deep nerves." (PMID 33669386, 2021). "It is a DNA repair-related gene, with an increased neurofibroma tumor load or malignant transformation, when overexpressed under the biallelic NF1 mutation background." (PMID 34566848, 2021). "Mice with a heterozygous mutation for Nf1 (mimicking NF1 patients) develop neurofibroma faster than their wild type littermates." (PMID 33413690, 2021). "One major advance is the FDA approval of the MEK inhibitor selumetinib for the treatment of NF1-associated plexiform neurofibroma." (PMID 34604034, 2021). "We also present a review of literature on MNF1 published between 2013 and 2020 with focus on plexiform neurofibromas and NF1-associated complications." (PMID 33853649, 2021). "Between 10% and 30% of NF1-associated plexiform neurofibromas undergo transformation to malignant PNST (MPNST), a highly aggressive sarcoma with a poor 5-year survival rate of less than 40%." (PMID 33669386, 2021).
neurofibroma (continued). "We discussed the need for a specific MNF1 follow-up guideline with focus on frequency of plexiform neurofibromas and NF1-associated complications." (PMID 33853649, 2021). "Roughly 50% of NF1 patients have a plexiform neurofibroma, which show a loss of the wild type NF1 allele in a Schwann lineage cell." (PMID 33808166, 2021). "Plexiform neurofibromas represent a rare variant (30%) of NF1 in which the spread of tumor cells along nerve fascicles leads to a diffuse mass of thickened nerve fibers." (PMID 35141069, 2021). "Other NF1-associated tumours comprise plexiform neurofibromas (30–50%), optic pathway gliomas (15–20%), MPNST (10–15%), and others." (PMID 35008787, 2021). "The NF1 p.(Met992del) variant that she carries has been previously associated with learning difficulties and a lack neurofibromas or Lisch nodules, consistent with her presentation." (PMID 32107864, 2020). "Constitutive Ras activation due to deficiency of neurofibromin 1 (NF1) on the other hand, leads to hyperproliferation of mast cell-rich neurofibromas, in a situation where RTK signaling seems to dominate Ras activation." (PMID 33193405, 2020). "A limited number of miRNA profiling studies examined human neurofibroma and NF1-derived MPNST tumor samples and implicated the involvement of several miRNAs in the malignant transformation of plexiform neurofibroma to MPNST18–21." (PMID 32076030, 2020). "An intriguing result was seen in mice with NF1 deficiencies, where normal mature myelinating Schwann cells exhibited no signs of tumor formation; however, when there was injury to the nerve, neurofibromas developed at those sites." (PMID 32182803, 2020). "These large NF1 locus deletions have been associated with a more severe phenotype including developing neurofibromas at an earlier age, having a lower mean IQ, abnormal facial features, and an elevated risk for malignant peripheral nerve sheath tumors (MPNST)." (PMID 32014052, 2020). "MPNST is a rare type of soft tissue sarcoma that can occur sporadically or in association with Neurofibromatosis type 1 (NF‐1), an autosomal dominant condition characterized by development of peripheral nerve sheath tumors called neurofibromas." (PMID 33063945, 2020). "Yet, to make mutations of neurofibromin 1 and neurofibromin 2 less probable we demonstrated the presence of both resulting proteins in neurofibroma of the celiac ganglia by immunohistochemistry." (PMID 32552868, 2020). "One NF1+/ex42del subject in our cohort presented with a giant CALM (>20 cm in diameter) along the left side; giant CALM is a rare NF1 manifestation reported in cases of segmental sporadic NF1 mutation with associated with plexiform neurofibroma and MPNST57–59." (PMID 32193437, 2020). "Children and adolescents with NF1 microdeletions had significantly more often cutaneous, subcutaneous and externally visible plexiform neurofibromas than age-matched patients with intragenic NF1 mutations." (PMID 32533297, 2020). "It is widely recognized that neurofibroma development in NF1 depends on a somatic NF1 mutation in a Schwann cell, rendering the cell deficient in NF1-encoded tumor suppressor protein neurofibromin function." (PMID 31767842, 2019). "We demonstrate that individuals with the NF1 p.Met992del pathogenic variant have a mild NF1 phenotype lacking clinically suspected plexiform, cutaneous, or subcutaneous neurofibromas." (PMID 30190611, 2019). "Although tumor development in the peripheral nervous system is a hallmark of NF1, a variety of CNS abnormalities, including neurofibroma, have been reported in NF1 patients." (PMID 31752929, 2019). "MPNSTs are highly malignant tumours; some MPNSTs are associated with NF1, and these tumours are mainly caused by the malignant transformation of neurofibromas." (PMID 31053152, 2019).
neurofibroma (continued). "In conclusion, we clearly confirmed that a 3-bp in-frame deletion of the NF1 gene, c.2970_2972del (p.Met992del), is associated with a mild phenotype lacking externally visible plexiform, cutaneous, or subcutaneous neurofibromas." (PMID 30190611, 2019). "A number of miRNAs and a lncRNA has been implicated in NF1-associated tumors, such as malignant peripheral nerve sheath tumors (MPNSTs) and astrocytoma, as well as in the pathognomonic neurofibromas." (PMID 31694342, 2019). "As mutations in the NF1 gene lead to abnormal cell growth, proliferation, and differentiation, individuals with NF1 frequently display neurofibromas, hyperpigmentation of melanocytes, and hamartomas of the iris." (PMID 31752929, 2019). "This composition is similar to another hallmark of NF1, which are the expansive growths within large nerves and plexuses referred to as plexiform neurofibromas (pNF)." (PMID 31107888, 2019). "We found that tranilast suppressed the expression of mesenchymal markers in NF1-mutated sNF96.2 cells as well as in neurofibroma cells from NF1 patients." (PMID 29666462, 2018). "Our findings thus suggest that tranilast and other EMT inhibitors warrant further investigation as potential therapeutic agents for NF1-associated neurofibromas." (PMID 29666462, 2018). "In NF1, MPNST tend to arise from plexiform neurofibromas as a consequence of NF1 mutations and LOH in Schwann cells, leading to activation of Ras signaling." (PMID 30055648, 2018). "A neurofibroma can be associated with NF-1; however, a solitary pelvic neurofibroma probably arises de novo without other organ involvement." (PMID 29426349, 2018). "We performed immunohistochemistry (IHC) on 74 MPNSTs (43 NF1-associated and 31 sporadic), 21 plexiform neurofibromas, and 9 atypical neurofibromas." (PMID 29796169, 2018). "Patients with NF1 mutation are predisposed to benign as well as malignant tumors like neurofibroma and malignant peripheral nerve-sheath tumors." (PMID 29966337, 2018). "Neurogenic neoplasms associated with NF1 include neurofibromas, ganglioneuromas and malignant peripheral nerve sheath tumours (MPNSTs)." (PMID 30187267, 2018). "Analysis of NF1 patient tumors and mouse models has led to the conclusion that the loss of function of NF1/Nf1 is an early and necessary step in the development of neurofibromas." (PMID 29987131, 2018). "NF1 syndrome is characterized by mutation-induced inactivation or more rarely complete germline loss of one NF1 allele that often leads to either dermal or plexiform benign neurofibromas." (PMID 30416982, 2018). "Bi-allelic inactivation of the NF1 gene through a “second-hit” mutation in a subset of Schwann cells has been demonstrated in neurofibromas from human patients." (PMID 30302402, 2018). "Neurofibromatosis type 1 (NF1) is caused by germline mutations in the NF1 gene and is characterized by café au lait spots and benign tumours known as neurofibromas." (PMID 29666462, 2018). "It would be interesting to study the tumor immunosurveillance activity of Type-I and Type-II NKT cells within the neurofibroma microenvironment, where Schwann cells are NF1-deficient." (PMID 29354122, 2017). "NF1 associated neurofibromas exhibit individual second NF1 hits, affecting precursor Schwann cells only." (PMID 29131833, 2017). "Recurrence risk for NF1-associated neurofibroma was increased compared to other patients with PNST, and the effect of this genetic status persisted after elimination of PNF from the calculation." (PMID 29214122, 2017). "Mutations in Neurofibromatosis-1 (NF1) produce neurofibromas and between 30% and 65% of children with NF1 mutations display learning disabilities and display significantly higher rates of autism, suggesting a causal relationship to autism." (PMID 29209173, 2017).
neurofibroma (continued). "NF1 exhibits variable clinical expression and is characterized by benign cutaneous lesions including neurofibromas and café-au-lait macules, as well as a predisposition to various types of malignancy, such as breast cancer and leukaemia." (PMID 28637487, 2017). "As a result of the NF1 protein’s ubiquitous expression and important role in cellular regulation, patients with mutations in the NF1 gene develop e.g., neurofibromas and other neoplasms and pigmentary abnormalities of the skin." (PMID 28202035, 2017). "Plexiform neurofibromas represent a special variant of NF-1 in which neurofibromas can arise from multiple nerves as bulging and deforming masses." (PMID 28166752, 2017). "There is increasing evidences that neurofibroma initiates through loss of NF1 function in the Schwann cell lineage, followed by a cascade of interactions with other cell types in the surrounding tumor microenvironment." (PMID 27517146, 2016). "This is also the first demonstration of differential staining in spontaneous and NF1-associated PNSTs, and in benign neurofibromas." (PMID 27655679, 2016). "The PNST TMA included 42 MPNSTs (spontaneous n = 26, NF1-associated n = 16), 35 neurofibromas (spontaneous n = 22, NF-1 associated n = 13), 11 schwannomas, and 18 normal nerves." (PMID 27655679, 2016). "Using conditional knockout models, it has been established that neurofibroma development can be stimulated through Nf1 loss of heterozygosity within the Schwann cell lineage when driven by Cre recombinase expression." (PMID 27482814, 2016). "Inactivation of the remaining NF1 wild-type allele is essential for neurofibroma formation, although genetically engineered mouse models have shown that a heterozygous NF1 (+/−) cell environment is important for its development." (PMID 25810463, 2015). "Patients with NF-1 are at greatest risk for developing sarcomas 10–20 years after the appearance of neurofibromas and, therefore, MPNSTs are frequently detected in adults 20–50 years of age." (PMID 25317349, 2014). "While loss of NF1 is clearly functioning to drive benign neurofibromas, it appears that further activation of Ras/PI3K/AKT/mTOR signaling is required for malignant transformation." (PMID 24681606, 2014). "In NF1 patients, loss of the Neurofibromin 1 gene (NF1) is required for benign neurofibroma formation, and additional genetic changes are required for transformation into MPNSTs." (PMID 24681606, 2014). "Distinguishing between isolated neurofibroma and those associated with NF-1 is important because of difference in clinical behaviour, treatment, and prognosis." (PMID 24860683, 2014). "Loss of Nf1 in mouse Schwann cells is sufficient for benign neurofibroma formation, but additional loss of Pten drives malignant transformation." (PMID 24681606, 2014). "The clinical characteristics in the NF1 diagnostic criteria include café-au-lait spots, neurofibromas, Lisch nodules, intertriginous freckling, typical osseous lesions and optic pathway gliomas." (PMID 24789688, 2014). "Although the histological identification of the NF1-associated neurofibromas is rather straightforward in practical terms, these tumors are notorious for exhibiting microscopic details that are apt to confound correct morphological diagnosis in an individual." (PMID 23890233, 2013). "Almost half of human MPNSTs develop from neurofibromas in patients with NF1 mutations and these have been reported to share similar CNA and transcriptome profiles with sporadic MPNSTs." (PMID 24009526, 2013). "Biallelic loss of function of the NF1 gene in neurofibromas promotes activation of the RAS signaling pathway." (PMID 23848554, 2013).